CD4 (CD4 molecule)
Diseases named in the same sentence as CD4 in open-access papers (continued):
Sharing a sentence is not in itself a finding about the gene and the disease.
tumor (continued). "Oestrogen deprivation of MCF-7 cells increased migration of total PBMCs and, specifically, CD4+ T cells towards tumour cells and slightly reduced CD11c+ and CD14+ cells." (PMID 34602068, 2021). "IL12A is a potent immunosuppressive cytokine produced by regulatory B cells, Treg cells, macrophages, dendritic cells, and tumor cells, which suppresses the effector functions of CD4+ and CD8+ T cells but strongly favors Treg proliferation." (PMID 34745101, 2021). "Guided by our CN findings, we formalized a computational scoring approach based on the spatial interactions of CD4+ T cells, tumor cells, and Tregs." (PMID 34795254, 2021). "In this context, the enrichment in DNA damage pathways in CD4+ T cells from BC patients is consistent with the notion that this population is stimulated in the presence of tumor environmental cues that act as stress inducers." (PMID 34386013, 2021). "As a result, increased IL-10 in TME directly suppressed the generation of CD4+ T cells, thereby impairing tumor immunity." (PMID 33957948, 2021). "When compared to blood counterparts, tumor-infiltrating senescent CD4+ T cells show similar surface phenotype but reduced cytokine production." (PMID 34386013, 2021). "EVs can stimulate both CD8+ cytotoxic T-lymphocytes and CD4+ T-helper cells, which are crucial for triggering an efficient anti-tumor immune response." (PMID 34722637, 2021). "The AKT/PI3K/mTOR signaling axis is usually antagonized by the product of phosphatase and tensin homolog gene (PTEN), a tumor suppressor gene that is downregulated in CD4+ TCL as well." (PMID 33969027, 2021). "Whereas the nonresponding tissue (#14) did not display changes in the relative distribution of T cells with respect to tumor cells, the tumor cells have more Treg, CD4, or CD8 T cells in their proximity in the responding tissue #15." (PMID 34564709, 2021). "A frank tumor-promoting activity is exerted by Tregs, CD4+ T lymphocytes expressing CD25 (the α subunit of IL-2 receptor) and the transcription factor Foxp3." (PMID 34681881, 2021). "In early tumour development, CD4+ T cells are driven to differentiate as Tregs rather that effector CD4+ T cells in the TDLN, promoting suppressive Treg responses that mimic peripheral self-tolerance to tumour antigen." (PMID 34141724, 2021). "To determine the tumor localization of injected CD4+T cells (following high salt stimulation), we performed in vivo cell tracking." (PMID 33918403, 2021). "To find new potential checkpoints, we investigated the cell-cell communications between tumor-promoting immune cells (CD4_CXCL13, CD4_FOXP3, CD8_CXCL13, CD8_ISG15, Mac_C1QA, Mac_ISG15, Mac_SPP1 and cDC3_LAMP3) and the ductal epithelial cells." (PMID 35087839, 2021). "Effector CD8+ cytotoxic and CD4+ helper lymphocytes exert anti-tumor effects upon T-cell receptor (TCR) recognition of antigens and proliferative stimulation by IL-2 protein." (PMID 34084172, 2021). "These activated B cells can contribute to anti-tumor immune response by inducing both CD4 + and CD8 + T cells response." (PMID 34952595, 2021). "A significant portion of CD4+ T cells in the tumor microenvironment express OX40 due to the recognition of tumor antigens, which presents an attractive therapeutic approach for anti-OX40 treatment." (PMID 34298809, 2021). "The prediction of CRC prognosis was modestly improved after adding the proportion of CD4+ T cells into the model, overall and by tumor stage." (PMID 34204621, 2021). "In CRC, myeloid DCs, the most common DC subtype associated with cell-mediated immunity and stimulation of naïve CD4+ T cells to the TH1 phenotype, are found in increased frequency at the tumor invasive front and are associated with lymph node invasion." (PMID 34944826, 2021). "The induction of IFN-γ and Th1 CD4 T cells activates anti-viral and anti-tumor cytotoxic T cells but can also downregulate Th17 responses." (PMID 35052724, 2021).
tumor (continued). "These in vivo data along with the in vitro cytotoxicity studies demonstrated that tumor-primed CD4+T cells from DLNs exerted the highest anti-cancer response." (PMID 33918403, 2021). "Tumor growth was greatly suppressed in OVA-MnJ-immunized but not OVA-aluminum-immunized mice, in line with prominently improved survival and increased levels of tumor-infiltrating CD4+ and CD8+ T cells, confirming the CTL-inducing activity of MnJ." (PMID 33767434, 2021). "Tadalafil had already demonstrated immune effects in HNSCC, such as a decrease in myeloid-derived suppressor cells, T-regs with increased CTL, and CD4+ in tumor tissue." (PMID 34885150, 2021). "There is increasing interest by viral and tumour immunologists alike in harnessing cytotoxic CD4+ T-cells for therapy." (PMID 34882759, 2021). "Tumor-infiltrating CD4+T cells isolated from the Sirt1flox/floxCd4-Cre mice displayed higher IL-9 production and IL9+ ratio accompanied by higher glycolytic activity, compared with CD4+T cells isolated from WT." (PMID 33748292, 2021). "The interaction between IDO and CD4+CD25+ regulatory T cells can play a key role in tumor immune escape, but is still controversial." (PMID 33767709, 2021). "In in vivo experiments, when further combined with CTLA-4, the primary and metastasis sites of the tumor were completely inhibited while substantial helper CD4+ and cytotoxic CD8+ T cells infiltrations were detected in the metastatic sites." (PMID 34656118, 2021). "In our hands, we found that only 12–15% of tumor infiltrating lymphocytes were from ex vivo activated CD4+T cells." (PMID 33918403, 2021). "CD4+ T cells can kill cancer cells directly, or kill tumor cells by stimulating and recruiting CD8+ T cells and other various immune cells indirectly." (PMID 33763372, 2021). "The results showed that autophagy-related lncRNAs were significantly correlated with tumor infiltration by CAFs, hematopoietic stem cells, CD4+ Th1, and other immune cells." (PMID 34897033, 2021). "Our results strongly suggest that GLS-010 has a high affinity to PD-1 with a stimulatory effect on CD4+ T cells in vitro and promising in vivo anti-tumor effects in mouse xenograft models." (PMID 34604074, 2021). "Puro+ cells (pink) are concentrated in some tumor areas, where clusters of highly translating CD4+ cells (brown) are found." (PMID 34787568, 2021). "TIL analysis demonstrated that the proportions of tumor-infiltrating CD4+ T cells were lower in the high-ATGPI group than in the low-ATGPI group in both the TCGA validation and UH cohorts." (PMID 34616731, 2021). "In the field of tumor immunology, the CD4+CD25+ regulatory T cell expressing transcription factor Foxp3+ has been described to highly inhibit anti-tumor immunity." (PMID 33987190, 2021). "We found that there was a high proportion of M0 macrophages, CD8 T cells, M2 macrophages, CD4 memory resting T cells, and M1 macrophages in the tumor tissues." (PMID 33955820, 2021). "Tumor reactive CD4+ T cells are a heterogeneous subset that have different effector functions depending on the type of cytokines they produce." (PMID 34262562, 2021). "HLA II molecules are involved in anti-tumor immunity and exogenous antigen presentation by CD4+ T cells." (PMID 34938740, 2021). "Analyses of these five TNFR2+ lymphocyte subsets in the tumors and spleens of vehicle-treated tumor-bearing mice revealed a significantly higher percentage of all of them—of the CD4+ arm, as well as the CD8+ arm—in TILs compared to splenocytes (Figure 2B1,B2)." (PMID 34201054, 2021). "For example, in a mouse model of ALK+ ALCL where expression of NPM-ALK was driven in T cells by a CD4 promoter, tumour formation was only compromised when both c-Jun and JunB were knocked-out, and double knock-out cells exhibited impaired proliferation." (PMID 33413671, 2021).
tumor (continued). "This score, termed the SpatialScore, calculates the physical distance ratio of each CD4+ T cell and its nearest tumor cell (“right” distance) relative to its nearest Treg (“left” distance)." (PMID 34795254, 2021). "Some of these cases progressed to a more aggressive phase consisting of ulcerated plaques, tumours, and the typical expression of cytotoxic markers, with one case changing from a CD4+ immunophenotype to a CD8+ phenotype." (PMID 34842638, 2021). "The tumor infiltrating T cells (both CD4+ and CD8+) of plinabulin-treated mice were functional, with increased capacity to produce intracellular IFN-γ, compared to control, upon ex vivo re-stimulation with anti-CD3 and anti-CD28 monoclonal antibodies (mAbs)." (PMID 33747968, 2021). "In contrast, the percentage of CD4+ T lymphocytes was significantly higher in peripheral blood than in tumor tissue." (PMID 34692375, 2021). "When the same experiments were performed using CD4+ cells from tumor-free mice engrafted with the IRAK1 KO cells, we saw the same MDSC-mediated suppression of proliferation." (PMID 34906138, 2021). "Tumor-infiltrating lymphocytes represent all lymphocytic cell populations, including CD4+, CD8+, and a small portion of B and NK cells that infiltrate the TME." (PMID 34235155, 2021). "Previous studies have shown that M1 tumor-associated macrophages (TAMs), CD8+ T cells, and CD4+ T cells played a crucial role in controlling tumor metastasis and prognosis." (PMID 34712666, 2021). "At this stage, the TME is typically immunosuppressive, e.g. enriched with regulatory T cells (Tregs), myeloid-derived suppressor cells (MDSCs), etc., and the infiltrating tumor-specific CD4 and CD8 T cells are often dysfunctional." (PMID 34867987, 2021). "Anti-tumor lymphocyte subtypes, like central memory CD4+ and CD8+ T cells, effector memory CD8+ T cells, cytotoxic cells, and monocytes were markedly enriched in patients with the low-risk scores (all P < 0.05)." (PMID 34747719, 2021). "In the TCGA-LUAD dataset, IGSF10 expression correlated positively with proportions of tumor-infiltrated B cells, CD4+ T cells, CD8+ T cells, neutrophils, macrophages, and dendritic cells." (PMID 34351868, 2021). "Tumor vasculature functionality depends on the interaction with M1/M2 like TAMs, CD4+/CD8+ T cells, and other stromal/immune cells." (PMID 33763348, 2021). "As CD4+ Th17 cells, γδ+ T cells, and ILCs are major IL-17 producers in the tumor microenvironment in the gut15, we investigated the cellular source of IL-17, which contributed to the overall increase in IL-17 levels seen in myeloid-miR-146a−/− mice during CRC." (PMID 33893298, 2021). "Frequencies of both CD8+ IFN-γ+ and CD4+ IFN-γ+ tumor-infiltrating lymphocytes (TILs) were also reduced within the gefitinib-treated group." (PMID 34075041, 2021). "There were fewer B cells, CD4+ T cells, CD8+ T cells, and endothelial cells in the tumor samples, while cancer-associated fibroblasts (CAFs) and macrophages were more in the tumor samples than in the normal controls." (PMID 33588380, 2021). "In this work, we use microarray data to analyze the phenotype and gene expression characteristics of tumor-infiltrating CD4+ T cells from TNBC patients." (PMID 33301062, 2021). "Accumulation of tumor Ag–specific CD4 T cells at tumor sites indicates that they play effector functions through, for instance, IFN-γ secretion." (PMID 33332284, 2021). "DCs are primed and then present these tumor-associated antigens to generate T cell responses including the production of CD8+ cytotoxic T cells (CTLs) and CD4+ T cells." (PMID 34134781, 2021). "LAIR2 was preferentially produced by activated CD4+ T cells and enhanced in vitro tumor invasion into collagen." (PMID 35008369, 2021). "Tumor antigen–specific CD4 T cells accumulate at tumor sites, evoking their involvement in antitumor effector functions in situ." (PMID 33332284, 2021).
tumor (continued). "Previous studies have suggested that bile acids, as tumor suppressants, can regulate the production and function of CD4, Th17, and Treg cells in peripheral blood, which impacts the body’s tumor immunity." (PMID 34901155, 2021). "Here, we summarize what is known about the effects of VitC on immune cells with anti-tumor activity (namely NK cells, CD4 and CD8 T cells, and γδ T cells) in the context of cancer immunotherapy." (PMID 34899716, 2021). "Tumor-infiltrating CD4+ cells accumulate into distinct transcriptome clusters, including early activated Tconv, uncommitted Teff, Th1 Teff, suppressive Treg and pro-tumorigenic Treg." (PMID 33602930, 2021). "The activation of IFN-γ can enhance their recognition by CD8 T cells as well as by CD4 T cells, and also unveil a key role in the promotion of tumor immunogenicity." (PMID 33628843, 2021). "CD4+ memory T cells and B cells are localized and enriched in tertiary lymphoid structures, which have shown benefits on many tumor types." (PMID 34250747, 2021). "Differently, the frequency of SP CD4+ T cells was higher in tumor than in I or NI TDLNs while DN CD4+ T cells showed significant differences only between tumor and NI TDLNs." (PMID 34386013, 2021). "Tumor-infiltrating LY6G MDSCs from orthotopic liver tumors treated with sorafenib dramatically increased CD4 T cells expressing IL-10 and TGF-and decreased CD8 T cell cytotoxicity." (PMID 34869376, 2021). "PD-L1expression is a tumor defense mechanism which leads to cytotoxic CD8+ T cell exhaustion and contributes to tumor immune evasion by shifting the maturation of naïve CD4+ cells into Treg." (PMID 34356899, 2021). "In this study, the correlation between CDKN1A and the immune system was assessed with the TISIDB database, and the results revealed that CDKN1A had the highest correlation with tumor-infiltrating lymphocytes including Tcm_CD4, pDC, Act_DC and Th1." (PMID 33621203, 2021). "The SpatialScore combines these principles by measuring the physical distances between 1) PD-1+ CD4+ T cells and tumor cells (i.e., effector function) and 2) PD-1+ CD4+ T cells and Tregs (i.e., suppressive function)." (PMID 34795254, 2021). "As opposed to CD103+CD8+ T cells, our in vivo studies showed a strong decrease in the frequency of CD103+FoxP3+CD4+ Treg in αV-knockout tumours, suggesting that CD103 expression in FoxP3+CD4+ and CD8+ T cells is regulated by distinct mechanisms." (PMID 34471106, 2021). "Within tumors, activated tumor-associated-MØs and/or -DCs set up a milieu to be either activating or suppressing through the production of chemokines that attract CD8+ T cells or CD4+ Tregs." (PMID 34721405, 2021). "Both IFNI and IFNγ drive polarization of CD4+ T cells towards the anti-tumor Th1 phenotype, preventing differentiation into the protumor Th2 phenotype." (PMID 33801234, 2021). "The number of CTLs and CD4+CD25+ cells in the tumor regions was then quantified as the density of CTLs and CD4+CD25+ cells in HCC tissues." (PMID 33441885, 2021). "Since the absolute cell number was not decreased, this reduction indicates the infiltration of conventional CD4+ T cells into the tumor." (PMID 34702924, 2021). "LAG3 expression widely suppresses anti-tumor immunity directly by impairing T/NK cells, and indirectly through impeding CD4+ T-cell functions via binding to MHC class II (MHC II) with a higher affinity than CD4." (PMID 33535613, 2021). "While these recent studies have clearly established that CD4+ T cells provide critical help for anti-tumour immune responses, the repertoire of antigens that CD4+ T cells recognise within the tumour microenvironment remains relatively unexplored." (PMID 32457487, 2021). "We also observed that PD-1 expression was higher in CD4+ T cells from tumor-bearing mice than tumor-free mice." (PMID 34649584, 2021). "In tumor tissue, overall CD4+ and CD8+ T cell populations were increased in tumor regions of Poly6-treated mice." (PMID 33499256, 2021).
tumor (continued). "Specifically, within the T cell population, [212Pb]VMT01 induced greater tumor infiltrating CD4+ helper T cells (63%) and CD8+cytotoxic T cells (29%) compared with control animals." (PMID 34359580, 2021). "Dai and colleagues reported that GRP94 on the surface of tumor cells also induces CD4+ and CD8+ T cell memory response." (PMID 34917098, 2021). "Relative to the colon, frequencies of CD3+ TILs and CD4+ TILs within leukocytes were increased in the tumor." (PMID 34680397, 2021). "By examining the functional properties of T cells in the tumor-draining LNs in mice that had received treatments for 5 weeks, we detected higher numbers of IFNγ and TNFα-producing CD4+ and CD8+ T cells after in vitro restimulation." (PMID 33408092, 2021). "AIP was positively correlated with tumor purity (r = 0.164, P = 6.27e−03), B cells (r = 0.2633, P= 8.94e−06), CD4 + T cells (r = 0.184, P = 2.06e−03) and macrophages (r = 0.138, P= 0.05)." (PMID 34784845, 2021). "Our increasing scientific knowledge on tumor-specific CD4 T cells is expected to provide new perspectives to develop optimized immunotherapy regimens." (PMID 34064410, 2021). "Human IL-10+ TIM-1+ Bregs can also be found infiltrating tumors and have been described to suppress CD8+ and CD4+ T cell anti-tumor responses." (PMID 33995344, 2021). "Studies generally also only investigated CD4+ T-cells belonging to either the TME or the periphery and not both, making connections between peripheral cytokine levels and tumour-associated immune cells difficult to establish." (PMID 34944729, 2021). "A lower SpatialScore (i.e., CD4+ T cells are closer to tumor cells than Tregs) suggests increased T cell effector activity, whereas a higher SpatialScore (i.e., CD4+ T cells are closer to Tregs than tumor cells) suggests increased T cell suppression." (PMID 34795254, 2021). "T-cell–specific expression of the human oncogenic fusion tyrosine kinase NPM-ALK under the control of the Cd4 promoter/enhancer element in mice results in 100% transformation and tumor development at a median age of 18 wk." (PMID 33310759, 2021). "Brain slices were immunologically stained for F4/80 to find tumor progression foci and Ki-67 to identify replicating tumor cells, in addition to the following T-cell phenotypic markers (CD4+, CD3+, CD8+, Foxp3, PD1)." (PMID 34944938, 2021). "It is of note that also various CD4+ T cell populations have been detected in tumors, although their role within the tumor microenvironment (TME) is less well understood compared to CD8+ CTLs." (PMID 34135885, 2021). "Targeting DC2s within these environments leads to improved DC migration, CD4+ T cell stimulation, and initiation of spontaneous tumor immunity." (PMID 34283809, 2021). "Specifically, the expression of KIFC1 was notably associated with tumor purity (r = 0.215, p = 5.37e-05) and the level of major infiltrating immune cell as B cells, CD8+ T cells, CD4+ T cells, macrophages, neutrophils, and dendritic cells." (PMID 35111813, 2021). "Tumor-infiltrating CD39+γδ Tregs in RSCRC significantly inhibited both CD4+/CD8+ T cell proliferation, and as expected, their suppressive functions were stronger than those of LSCRC." (PMID 34283812, 2021). "NK cell (p < 0.001), CD8 + T cell (p < 0.001) and myeloid dendritic (p < 0.001) cell were higher in normal tissue estimated in MCP while CD4 + T cell (p < 0.01) was lower expressed in tumor tissue through calculation in EPC." (PMID 34344378, 2021). "Tregs (FOXP3+, CD25+, CD4+) contribute to the development of an immunosuppressive tumor microenvironment, inhibiting the activation and expansion of tumor-specific effector T cells." (PMID 34829955, 2021). "We detected the early production of several inflammatory cytokines in the CD4+ T cells of tumor-bearing STAT1-/- iso mice, with higher levels of IFN-γ, IL-6, and IL-17, compared with their WT counterparts." (PMID 34299314, 2021).